INS (insulin)
Diseases named in the same sentence as INS in open-access papers (continued):
Sharing a sentence is not in itself a finding about the gene and the disease.
Hyperglycemia (continued). "Unfortunately, current strategies with insulin infusion are non-physiological, thus supporting the need to develop robust and novel strategies to restore b cells and insulin production to more effectively treat hyperglycaemia." (PMID 35674842, 2022). "Moreover, in obese ob/ob mice, C646 treatment through intraperitoneal injection (30 nmol/g/day) for 10 days significantly improved insulin sensitivity and hyperglycemia without significant changes in body weight." (PMID 35074429, 2022). "Recent observations suggest that basal insulin alone may be efficacious in patients with CFRD without fasting hyperglycemia." (PMID 35887806, 2022). "In insulin-resistant patients, ABA supplementation could contribute to the reduction in post-prandial hyperglycemia, in conjunction with oral hypoglycemic drugs, by synergizing with the action of endogenous insulin, via a different signaling pathway, eliciting an increased muscle glucose uptake." (PMID 35736456, 2022). "We found two phenotypes of GC-induced hyperglycemia: a milder type which may be treated with no or low doses of insulin, and a severe type which requires basal-bolus or premixed insulin." (PMID 34986826, 2022). "In addition, another study examined the antihyperglycemic effect of German chamomile using STZ-diabetic rats and found that it reduces hyperglycemia without affecting insulin levels." (PMID 36160451, 2022). "Importantly, hyperglycemia-induced changes in the mPFC were almost not reversed by the 4-week insulin treatment." (PMID 36552776, 2022). "Glycemic fluctuations from 33 to 2.1 mmol/l (594 to 38 mg/dl) according to glucometer measurements were observed against the background of Lis-Pro insulin therapy, while no hyperglycemia was registered in venous blood and in the interstitial fluid concomitantly with the values found by glucometer." (PMID 36376919, 2022). "This behavior occurs because the IOB is constrained with the same boundary all the time, and thus, when the variations towards hyperglycemia occur(which have a time-random component), the control action is restricted, and the insulin doses delivered are not enough to counteract the variations." (PMID 35265035, 2022). "Importantly, the GLUT1 transporter is independent of insulin, enabling cancer cells to substantially uptake glucose, especially in the context of hyperglycemia (e.g., untreated or insufficiently treated diabetes)." (PMID 36230918, 2022). "High blood sugar or hyperglycemia could result from insulin resistance or pancreatic cells not producing enough insulin to accommodate the sugar level in the blood." (PMID 35321328, 2022). "Our previous study, which used NCD‐fed rats, showed that food restriction by pair‐feeding to E2 replacement group in the PL group ameliorated hyperglycemia in the OVX rats but failed to mimic the effects of E2 replacement on basal levels of insulin signaling components, Akt2 and AS160." (PMID 35238495, 2022). "Patients without pretreatment insulin therapy had a slow onset of hyperglycemia (after the third injection of pasireotide LAR) that could be managed with oral antidiabetic medication only." (PMID 35090028, 2022). "The concept of PHH corresponds to hypoglycemia that recover to hyperglycemia in any circumstance (e.g. excess of carbohydrate intake during hypoglycemia, lack of insulin coverage, modification of physical activity level) and as such is not related to the controversial Somogyi effect." (PMID 35832426, 2022). "It does not attempt to set a different basal insulin delivery rate to mitigate hyperglycemia." (PMID 36502149, 2022). "It includes a group of metabolic diseases characterized by hyperglycemia, in which blood sugar levels are elevated either because the pancreas does not produce enough insulin or because cells do not respond to the produced insulin." (PMID 36296520, 2022).
Hyperglycemia (continued). "Not all patients required a basal-bolus insulin therapy regimen and the bolus-correction regimen may be an option for patients with non-severe hyperglycemia." (PMID 35758838, 2022). "In the pancreatic β cell, GLUT2 acts as a glucose sensor that detects small changes in glucose levels leading to increased insulin secretion, and the lack of such transporters in the immature pancreas are likely to impact the β cell’s response to hyperglycemia." (PMID 36361703, 2022). "However, in clinical practice acute administration of insulin to a neonate with hyperglycaemia is, in most cases, not urgent." (PMID 36542240, 2022). "On subinterval analysis we observed a TpTe shortening during hyperglycaemia in men rather than women, and this may be due to the presence of exogenous insulin, but the sample size and unbalanced cohorts limits our analysis." (PMID 35596784, 2022). "Noteworthy, the treatment with MSC-EVs did not significantly affect insulin tolerance or ameliorate hyperglycemia, indicating that inflammation or other mechanism altered by EVs may play role, at least in this particular setting." (PMID 34110587, 2022). "Furthermore, manipulation of gut microbiota or knockdown of FMO3 in insulin-resistant mice inhibited TMAO production, reduced PERK activation and suppressed FoxO1 in the liver, which may prevent the development of hyperglycemia." (PMID 35982495, 2022). "This gives rise to some uncertainty about the positive effects of insulin postulated by other studies, and insulin may not entirely reverse the adverse effects of hyperglycemia on bone growth and metabolism." (PMID 36558969, 2022). "The hyperglycemia of non-diabetic patients (Group 1) was generally mild and transient, falling below the threshold of 126 mg/dl (7 mmol/l) within a few days and, in fact, only in 9.6% of cases a short insulin treatment was administered." (PMID 36038896, 2022). "No hyperglycemia was reported in ADSL-deficient patients, and only transient hypoglycemia was described in ATIC-deficient patients that was associated with increased activation of the insulin pathway in hepatocytes." (PMID 35323684, 2022). "However, glargine did not control postprandial hyperglycaemia, making it necessary to supplement with short-acting insulin at mealtimes." (PMID 35152907, 2022). "Likewise, optogenetic stimulation of VMHNOS1 neurons causes robust hyperglycemia via activation of CRR (i.e., glucagon and corticosterone), without a suppression on insulin release." (PMID 35619170, 2022). "The expression of both SNAT2 and PAG was decreased by hyperglycemia and was not restored with insulin treatment, which may have explained the lack of change in Glu in the STZ and SI groups compared with the CTL group." (PMID 36552776, 2022). "Similarly, the extensive use of olive oil in MedDiet can offset the adverse effects of inflammation, oxidative stress, and acute hyperglycemia on endothelial function and recover the protective action of GLP-1 on insulin secretion, endothelial function, and inflammation in T2DM." (PMID 35807957, 2022). "It should be underlined that although blood glucose level in STZ-treated animals was notably higher than in controls, all pigs with hyperglycemia survived the duration of the experiment in good condition, and none of the pigs required exogenous insulin supplementation." (PMID 35562954, 2022). "For instance, it was found that MLD-STZ administration resulted in stable and long-lasting hyperglycemia in rats with no insulin response to glucose administration and significant morphological derangements in the islets 3 months after receiving MLD-STZ treatment." (PMID 35159301, 2022). "Nonetheless, hyperglycemia associated with T1DM and T2DM is also associated with hyperlipidemia and hepatic steatosis, an effect that is attributed to increased mobilization of FFAs from the adipose tissue due to lack of insulin." (PMID 35878267, 2022).
Hyperglycemia (continued). "At present, we can only speculate that while hyperglycaemia is not a potent enough suppressor of glucagon secretion, the degree of insulin secretion was sufficient to inhibit excess glucagon secretion." (PMID 34951657, 2022). "Even when well regulated, blood glucose will vary and acceptable blood glucose targets during insulin treatment are typically above the reference range for nondiabetic dogs, so a dog may experience hyperglycemia at various times during the day." (PMID 35213623, 2022). "To assess whether uric acid, insulin, and their combination can foster inflammatory responses in endothelial cells exposed to hyperglycaemia, we treated HUVEC with 25 mM glucose for 1 week, with the same concentrations of uric acid, insulin, and their combination." (PMID 35503137, 2022). "Performing different clamp experiments, Stegenga and colleagues could show that hyperglycemia triggers fibrin synthesis and stimulates coagulation irrespective of insulin levels; hyperinsulinemia, on the other hand, impairs fibrinolysis." (PMID 36211489, 2022). "However, the STAM mouse is recognized as a type 1 diabetes-related NASH model with hyperglycemia, reduced body weight gain, and lack of insulin secretion and fatty acid mobilization from adipose tissue." (PMID 35203369, 2022). "GLUT4 facilitates insulin-promoted glucose uptake into adipose tissue and muscle, and reduced GLUT4 expression levels lower insulin-mediated glucose uptake; exacerbated hyperglycemia may be the mechanism of action, as indicated by heightened glucose intolerance on the basis of an IPGTT." (PMID 34564583, 2021). "However, in some patients with MODY, hyperglycemia can be controlled by prescribing oral antidiabetic drugs (e.g., sulfonylureas), without the use of insulin." (PMID 33604390, 2021). "However, after 12 weeks, the dailydoses of insulin were similar, suggesting that the dose of insulin at the start was not enoughto overcome post-prandial hyperglycemia." (PMID 35111536, 2021). "However, insulin therapy did not lead to mothers with severe hyperglycemia achieving a target of glycemic control because of insulin resistance pathophysiological features in GDM." (PMID 34093439, 2021). "Moreover, human studies evidenced that the GIP receptors was down regulated in adipose tissue in insulin-resistant states, but acute infusion of GIP under hyperinsulinism and hyperglycemia conditions promoted adipose tissue glucose uptake and triglyceride hydrolysis." (PMID 35054422, 2021). "In Sprague Dawley rats given a 20% fructose drink, which provides a model of hyperinsulinemia and insulin resistance, but not hyperglycemia, 8 weeks of paeoniflorin treatment (10, 20, 40 mg/kg/day, oral gavage) improved glucose tolerance to a similar extent as the insulin sensitizer pioglitazone." (PMID 35098034, 2021). "Accurate insulin dosing is critical to maintain glucose levels within the normal glycemic range and to prevent acutely dangerous hypoglycemic episodes as well as the long‐term consequences of hyperglycemia." (PMID 33931977, 2021). "This suggests a mechanism of transient hyperglycemia induced by a transient inflammation of the islet cells of the pancreas by SARS‐CoV through binding of SARS‐CoV to the ACE2 present on islet cells, resulting in a transient insulin dependent DM, which resolved with resolution of disease." (PMID 32589756, 2021). "Consequently, glucagon and hepatic glucose levels that rise during fasting are not suppressed with a meal due to inadequate insulin concentration, increased insulin resistance, and increased fat breakdown with hyperglycemia." (PMID 34445786, 2021). "The reason why the effects of stress hyperglycemia on the outcome are not influenced by the type of treatment, whether aggressive or standard insulin treatment, remains a puzzle." (PMID 34659090, 2021). "Additionally, hyperglycaemia decreased by more than 50% at camp compared to a home setting, without requiring increases in basal or bolus insulin doses." (PMID 34277978, 2021).
Hyperglycemia (continued). "In this study, hyperglycemia did not affect any of the evaluated steps of insulin cascade." (PMID 34948265, 2021). "Moreover, our derived findings confirm clozapine-induced aggravation of hyperglycemia and demonstrate that clozapine-engendered lowering of GLUT4 expression and Akt phosphorylation in insulin signaling was related to the augmentation of IR, impairment of glucose tolerance, and reduction of IS." (PMID 34206460, 2021). "Thiazolidinediones can prevent or reverse the toxic effect of hyperglycemia on tyrosine kinase, promote the phosphorylation of IRS‐1, increase the level of GLUT‐4 mRNA and protein in the skeletal muscle of insulin‐resistant mice, and promote the translocation of GLUT‐4 in the skeletal muscle." (PMID 33650786, 2021). "In the current study, while both male and female diabetic rats had higher body weight and hyperglycemia compared with non-diabetic control rats, the female diabetic group exhibited higher adiposity, triglyceride, and insulin levels than control or male diabetic rats." (PMID 34366875, 2021). "Moreover, while chronic GCG stimulation exhibits glucose intolerance, acute GCG agonism at a lower dose, which is not able to evoke hyperglycaemia, enhances glucose tolerance and improves insulin sensitivity." (PMID 34072172, 2021). "An earlier study, however, indicated that SIRT1 regulates pancreatic islet formation and differentiation through deacetylating FOXA2, and that pancreatic disruption of SIRT1 resulted in a progressive hyperglycemia together with glucose intolerance and a lack of insulin." (PMID 33806509, 2021). "In first trimester, the foetus does not have the ability to secrete insulin, which may result in foetal hyperglycaemia in the event of relative maternal insulin resistance." (PMID 34043700, 2021). "T2DM is characterized by insulin resistance, a relative lack of insulin, and hyperglycemia." (PMID 33869312, 2021). "Through the results of oral glucose tolerance tests (OGTTs), peritoneal insulin tolerance tests (IPITTs), IR index (HOMA-IR) and serum insulin tests, they found that intravenous injection of sEVs from MSCs (hucMSC-sEVs) can effectively alleviate hyperglycemia in T2DM rats." (PMID 34987478, 2021). "In our study, hyperglycemia was defined as blood glucose > 150 mg/dl but no infant needed insulin." (PMID 34785747, 2021). "Consequently, during the second trimester, the fetal pancreas, which is now capable of secreting insulin, can now respond to hyperglycemia and secretes insulin autonomously irrespective of glucose stimulation." (PMID 33577577, 2021). "Consequently, the β-cell can no longer compensate for the peripheral insulin resistance in response to ingested glucose and promotes the onset of hyperglycaemia." (PMID 33794975, 2021). "SARS-CoV-2 infects the pancreas through angiotensin-converting enzyme 2 (ACE2), where it is highly expressed compared to other organs, leading to pancreatic damage with subsequent impairment of insulin secretion and development of hyperglycemia even in non-DM patients." (PMID 34124187, 2021). "This hyperglycaemia results from a lack of insulin secretion and/or a failure in insulin action." (PMID 34959301, 2021). "The overall lack of increased insulin and hyperglycemia is surprising." (PMID 34095511, 2021). "Hyperglycaemia is common in infants with NEC, at least in its early phase, and has been associated with an increase in late mortality, without notable effects of insulin on NEC or other morbidities." (PMID 33946896, 2021). "Continuous subcutaneous insulin infusion (CSII) as an important transient aggressive glycemic control method to protect β-cells and induce normoglycemia accompanied with the restoration of insulin sensitivity has been used in T2DM patients with severe hyperglycemia." (PMID 34136580, 2021). "Thus, elevated serum insulin level mediated by 1,25D in vivo study might be an explanation for the activation of PI3K/Akt signaling by 1,25D in hyperglycemia environment." (PMID 33450223, 2021).
Hyperglycemia (continued). "Notably, the odds of hyperglycemia was higher in participants who were on metformin and vildagliptin compared with two other regimens (metformin and glimepiride; metformin, insulin glargine U100, and human regular insulin) independent of treatment dosage." (PMID 34305809, 2021). "Moreover, PI3K inhibition can result in hyperglycaemia as PI3K mediates cellular responses to insulin, which leads to an increasing release of insulin in a feedback manner and re-activate PI3K pathway in tumor models in mice, thus ultimately causing PI3Ki resistance." (PMID 33790792, 2021). "If hyperglycemia is not controlled with glucose lowering agents, insulin is the preferred option." (PMID 34830886, 2021). "And, conversely, when there is a lack of insulin, exercise can lead to hyperglycemia or ketosis." (PMID 33633280, 2021). "Whether the detrimental effects of early hyperglycemia exposure affect the pancreatic function, including the production of insulin producing cells, is lacking in the current study model." (PMID 34639069, 2021). "However, when beta cell compensation fails to meet increasing insulin demands imposed by insulin resistance, glucose intolerance first becomes apparent as mild and later overt hyperglycemia that characterizes a full-blown T2DM." (PMID 34359828, 2021). "However, this definition based on insulin doses and HbA1c is not sufficient in terms of glycemic variability, insulin sensitivity, and episodes of hypoglycemia and hyperglycemia." (PMID 33485357, 2021). "Likewise, hyperglycemia should be avoided and patients should not be administered insulin shortly before FDG-PET/CT." (PMID 33827655, 2021). "Although the mechanism of reduced neuronal proliferation is not well-known till now, evidence suggests that lack of insulin and/or hyperglycemia in the brain may be contributing factors." (PMID 34568337, 2021). "Treatment of hyperglycemia in patients with COVID-19 has been particularly difficult as many centers have attempted to limit insulin infusions to preserve PPE and minimize health care provider exposure, as treatment with insulin infusion require hourly finger stick blood glucose checks." (PMID 33992101, 2021). "The increase in the plasma levels of adenine nucleotides insinuates subsequent overactivation of the fuel-sensing enzyme AMP-activated protein kinase (AMPK) in insulin resistant individuals, or AMP elevation may predate the hyperglycemia as an upstream regulator of glucose uptake in the whole body." (PMID 33918080, 2021). "Perhaps the implementation of rigorous protocols of early insulin administration in cardiac ICU patients with stress hyperglycemia could shed light on the question of whether or not early administration of insulin during AMI alters prognosis." (PMID 33463901, 2021). "In addition, we chose to assess hyperglycaemia with a hyperglycaemic clamp as in previous studies, but the endogenous insulin production was not supressed as in a hyperinsulinaemic euglycaemic clamp." (PMID 33739980, 2021). "Hence, GIP may assume greater importance to maintain insulin secretion in obese individuals who have decreased GLP-1 secretion, preventing hyperglycemia." (PMID 33320449, 2021). "However, no specific insulin therapies appear to have significantly distinct advantages both for an effective treatment of hyperglycemia and for their possible positive impact on the clinical course of CF." (PMID 34017312, 2021). "It is known that AR is important for insulin production, and the degree of hyperglycemia in high GTTs may outstrip the capacity for insulin production regardless of insulin sensitivity." (PMID 34599964, 2021). "However, the maternal-derived or exogenously administered insulin does not cross the placenta, and the fetus responds to maternal hyperglycemia by hyperinsulinemia, which reduces fetal blood glucose levels, increases fetal adipose tissue, and enhances growth." (PMID 33803995, 2021).